EPCAM (epithelial cell adhesion molecule)
Diseases named in the same sentence as EPCAM in open-access papers (continued):
Sharing a sentence is not in itself a finding about the gene and the disease.
tumor (continued). "In contrast, EpCAM was heterogeneously expressed in tumor samples and positive in normal tissue." (PMID 33276608, 2020). "In this regard, different studies shown that anti-EpCAM aptamer functionalized nanocarriers could effectively improve the delivery of anticancer drugs to tumor cells." (PMID 32383027, 2020). "Another class consisting of both the TME and tumour was characterised by lower expression of most proteins, with some ROIs expressing high levels of Ki-67 and EpCAM, whereas a third class was characterised by relatively heterogenous expression of all proteins (right)." (PMID 33261133, 2020). "We then analyzed Nrf2 and EpCAM transcript levels by qRT-PCR and found that both transcripts were increased in cisplatin-resistant tumor cells, suggesting that resistance to cisplatin is due in part to an increased level of Nrf2 transcriptional activity and EpCAM overexpression." (PMID 32814771, 2020). "The selective targeting of the NDDSs through anti-EpCAM-specific aptamer could be considered as an effective targeting option to deliver chemotherapeutic agents into the tumor microenvironment." (PMID 32383027, 2020). "In addition to being a valuable marker for the EMT status of tumor cells, EpCAM is also functionally involved in the regulation of EMT." (PMID 32507912, 2020). "Tumor-associated macrophages (TAM), a critical component of immune cells in the tumor microenvironment are positively correlated with the EpCAM+ population and enhance cancer stem cell-like properties via upregulation of CSC transcription factors Bmi1 and Klf4." (PMID 32466488, 2020). "Flow cytometry analysis of FVS− viable dormant tumor cell lines that regrew ex vivo had similar characteristics by the expression of neu antigen, the epithelial cell marker EpCAM, and a predominant CD24+CD44+ fraction over CD24-CD44+ cancer stem cell-like fraction." (PMID 33115528, 2020). "Furthermore, only a small proportion (20%–35%) of HCCs express EpCAM, although at least a weak EpCAM expression in >10% of tumors was observed in 87 of 131 different tumor categories." (PMID 32443747, 2020). "We selected three putative tumor markers and EpCAM as an epithelial cell marker." (PMID 33276608, 2020). "Hence, the enrichment of rare EpCAM-positive systemic tumor cells in the blood in the frame of liquid biopsies has the potential to evaluate disease outcome including the patients’ burden of metastatic cells." (PMID 32507912, 2020). "As no quantitative information about the uptake of DARPin-based agents targeting EpCAM in SKOV-3 tumor model was available, we chose a wide range of concentrations based on our previous experience with other types of scaffold proteins, affibody molecules, and ADAPTs." (PMID 32392820, 2020). "However, the expression of EpCAM significantly varies in normal kidney tissue, and it ranged from moderate to strong in our tumor samples, but was enriched in their exosomes." (PMID 33276608, 2020). "EpCAM antibodies are commonly used to detect epithelial cells in flow cytometry, for example, for detecting leptomeningeal metastasis of solid tumors in liquor or isolating epithelial cells from normal and tumor tissue." (PMID 32255255, 2020). "Although many studies have reported that the expression of CD44, CD44v, CD133, EpCAM and ALDH1A1 is associated with tumor progression and can be used to predict patient’s outcome, their prognostic significance in the recurrence of CCA in patients has not been elucidated." (PMID 32039729, 2020). "In view of these results, the loss of EPCAM expression in those neoplasms where EPCAM was not expressed in their normal counterpart was considered noninformative." (PMID 33003511, 2020). "Further ImageStream analysis revealed the expression of epithelial cell adhesion molecule (EpCAM) and exosome specific surface markers, including CD9, CD63, tumor susceptibility gene 101 (TSG-101), and CD81 confirming the tumor cell-derived vesicles as exosomes." (PMID 32456301, 2020).
tumor (continued). "Catumaxomab is a 150 kDa hybrid IgG2 like molecule targeting epithelial cell adhesion molecule (EpCAM), a tumor antigen and CD3 on the T cells in contrast to Blinatumomab, which is a 55 kDa bispecific T cell engager (BiTE) targeting CD19 on the cancer cell and CD3 on the T cell." (PMID 32341754, 2020). "Multiple cellular functions of EpCAM may deploy in dependency of tumor types and localization, and might differently affect single cells within tumors." (PMID 32507912, 2020). "Glycosylation of EpCAM may impact on EpCAM stability and expression in tumor cells, as it was found increased in cancerous versus healthy tissue." (PMID 32507912, 2020). "Even in the pluripotent EC line NCCIT displaying EpCAM surface expression only on half of the tumor cells, the EpCAM/CD3-specific bAb still induces marked GCT lysis in the presence of PBMC, amounting to 56.5 ± 4.8%, 59.1 ± 3.9%, and 52.1 ± 8.5% at 1, 0.1, and 0.001 μg/mL, respectively." (PMID 32438548, 2020). "Differential EpCAM expression demonstrates distinct tumor biology in athymic mouse models." (PMID 32547703, 2020). "EpCAM has been recognized as an additional marker for CSCs in different tumor types." (PMID 32257947, 2020). "Moreover, under the influence of IL-6, the concentration of EpCam+CD44hiCD24low tumor stem cells increased dramatically (2.5 times), and the EpCam+CD44lowCD24– concentration decreased two-fold." (PMID 32523653, 2020). "THD treatment exhibits anti-tumor effect on CSCs EpCAM+/CD44+ subpopulations isolated from HCT116 through apoptosis induction via mitochondrial pathway since THD promotes upregulation of caspase-3 and Bax and downregulation of Bcl-2 suppressing proliferation and invasion." (PMID 32923398, 2020). "Considering that EpCAM is also expressed in tumor-initiating cells, antibody-based therapies against EpCAM may kill not only proliferating cancer cells, but also drug-resistant dormant CRC cells." (PMID 33154781, 2020). "However, in the NASH microenvironment, EpCAM+ CSCs showed aggressive tumor growth while EpCAM- Hepa1-6 cells demonstrated incidental tumor initiation (2/10 mice with tumors, much smaller in size and volume compared to EpCAM+ tumor)." (PMID 32547703, 2020). "In contrast, in the pluripotent EC line NCCIT, only 50% of tumor cells displays EpCAM." (PMID 32438548, 2020). "We used it to verify that EpCAM-expression was heterogeneously distributed within tumor nodules." (PMID 33225916, 2020). "A caveat of EpCAM-based detection techniques is the morphology of the tumor and CTCs." (PMID 32197486, 2020). "Interestingly, expression data from immune ROIs indicated that the presence of EpCAM and cytokeratin was associated with better patient OS, while the presence of CD34, CD3, and ICOS in tumour ROIs was associated with better patient OS." (PMID 33261133, 2020). "Macroscopically, all 4 mice in EpCAM-High group had tumor growth confirmed by ultrasound, while only 1 out of 4 mice in EpCAM-Low group were confirmed with tumor growth (significantly lower in tumor size and volume compared with EpCAM-High group tumors)." (PMID 32547703, 2020). "Also, claudin-7 knockdown cells displayed decreased tumour growth and impaired migration and motility, due to the recruitment of EpCAM with claudin-7." (PMID 32091301, 2020). "For these reasons, the antibody-coated magnetic platform using EpCAM may be at dismal to detect CTCs42, and only 70% tumor cells out of 134 types could be detected and a major segment of invasive tumor cells remains undetected by EpCAM43,44." (PMID 32561829, 2020). "Moreover, EpCAM is a target marker on tumor cells, and it is also expressed on the membrane of other liquid biopsy analytes, such as EVs." (PMID 32764280, 2020). "EpCAM was expressed in normal tubular and tumor cells at a similar, heterogenous expression level." (PMID 33276608, 2020). "EpCAM is also used as a marker for the detection of circulating tumor cells (CTCs)." (PMID 33490064, 2020).
tumor (continued). "EpCAM can also be found in disseminated tumour cells and circulating tumour cells." (PMID 32046162, 2020). "Importantly, EpCAM is the central target molecule for the enrichment and characterization of systemic tumor cells with prognostic and metastatic potential." (PMID 32507912, 2020). "Therefore, CTCs in the presence of EpCAM are strongly correlated to tumor aggressiveness, and this marker allows adequate stratification of HCC patients for curative or systemic therapy." (PMID 32610709, 2020). "EpCAM is an attractive target for this purpose due to sufficiently high expression in OC, and DARPins seem to be a promising type of targeting vectors because their small size permits efficient diffusion into tumor extracellular space." (PMID 32392820, 2020). "A next generation of EpCAM-targeted drugs that are selectively activated in the tumor microenvironment may finally allow to leverage this target antigen." (PMID 32507912, 2020). "In contrast, administrating EpCAM-siPKCι aptamer deterred tumor propagation." (PMID 32820156, 2020). "Analysis of T cell stimulation in co-culture settings with tumor cell lines presenting different EpCAM/EGFR expression profiles demonstrated costimulatory capacity of all fusion proteins in a broad range of target expression, enhancing the effect of suboptimal bispecific antibody concentrations." (PMID 32504247, 2020). "For instance, an EpCAM aptamer was shown to have better tumor penetration, more homogeneous distribution and better retention in vivo than an EpCAM antibody in a mouse xenograft tumor model." (PMID 32226524, 2020). "EpCAM, αvβ6 and FRα were expressed on the cell membranes of metastatic tumor cells." (PMID 32545676, 2020). "Furthermore, EpCAM served to enrich, identify, and characterize metastatic cells that have disseminated from primary tumor into blood and bone marrow of advanced carcinoma patients." (PMID 32507912, 2020). "In another study, EpCAM-positive circulating tumor cells were identified from HCC patients undergoing curative resection, which displayed stem cell-like and EMT phenotypes that were likely to cause tumor recurrence after surgical resection." (PMID 32466488, 2020). "Since cathepsins are often expressed by metastatic cancer cells, overexpression of EpCAM can thus lead to stronger inhibiting effects that may protect these tumour cells against cathepsins during tumour progression." (PMID 32046162, 2020). "Besides affecting intercellular adhesion, EpCAM influences important other functions relevant to tumor progression including cell proliferation and cancer stemness, which suggests an active role of EpCAM in cancer metastasis." (PMID 31225512, 2019). "It was shown that DNA methylation could prevent amplification of a transfected EPCAM gene and this mechanism was suggested to occur in tumor cells." (PMID 31225512, 2019). "Clearly, the reduction in the transduction efficiency of EpCAM-targeted ΔRGD viruses was more pronounced in 3D cultures as compared to 2D cultures, suggesting independently contributing effects of both the type of receptor and the tumor architecture." (PMID 31811202, 2019). "Nuclear pSmad2/3 was found in F4/80+ myeloid cells, gp38+ fibroblasts, and EpCAM+ tumor cells." (PMID 31511510, 2019). "Besides tumor epithelial cells (EpCAM+; epithelial cell adhesion molecule), CAFs (FAP+; fibroblast activation protein), immune cells (CD45+), and endothelial cells (CD31+) are the main cell types in ascites." (PMID 30710055, 2019). "Epithelial–mesenchymal transition (EMT) is implicated in the metastatic process and presents a challenge to epithelial cell adhesion molecule-based detection of circulating tumor cells (CTCs), which have been demonstrated to be a prognostic indicator in metastatic breast cancer." (PMID 30606259, 2019). "EpCAM is a transmembrane glycoprotein involved in epithelial cells adhesion, through homophilic and heterophilic interactions and represents a marker for circulating tumor cells." (PMID 35582268, 2019).
tumor (continued). "Likewise, we did not observe differences in the peripheral blood composition between gp130FF and gp130FF; c-KitW-sh/W-sh compound mutants and we confirmed that EpCAM positive tumor cells lack c-Kit expression." (PMID 31227713, 2019). "Interestingly, we further found that the frequency of mast cells was positively correlated with CXCL12 production, which most likely derived from EpCam+ tumor cells in the GC microenvironment." (PMID 30808413, 2019). "One study presented that linc00152 can bind to the promoter of epithelial adhesion molecule (EpCAM) gene, and thus, induce cell proliferation and tumor growth by inducing the transcriptional upregulation of EpCAM and activation of the mammalian target of rapamycin pathway." (PMID 31896236, 2019). "Since tumor-derived EVs in ascites represent only a small fraction of the total number of EVs present, we have developed an immunoaffinity-based capture method using microbeads coated with anti-EpCAM antibody." (PMID 31278254, 2019). "In addition, EpCAM is one of the main biomarkers of circulating tumor cells and microemboli in blood." (PMID 30871104, 2019). "EpCAM is an adhesion molecule overexpressed in many quickly proliferating tumours, including CRC." (PMID 31662751, 2019). "Epithelial cell adhesion molecule (EpCAM) is a widely used marker for capture of circulating tumor cells and its adhesive interactions may affect metastasis." (PMID 30988307, 2019). "Therefore, future research should be to combine EpCAM antibodies with antibodies to other positive tumor cell surface markers to achieve the best results." (PMID 31767014, 2019). "This would suggest that for the patient under study, anti-EpCAM therapies may have limited effect on metastatic tumor cells in the bone marrow." (PMID 31798587, 2019). "T cell-mediated cytotoxicity, cytokine secretion, expression of activation markers, and proliferation were directly induced in T cells treated with the novel CD3xEpCAM bispecific molecule in vitro in the presence of epithelial cell adhesion molecule (EpCAM) expressing tumor cells." (PMID 31825302, 2019). "EPCAM were generally defined as a potential tumor marker and immunotherapy target, it was also suggested that inactivation of this gene could lead to prominent placental abnormalities." (PMID 31882783, 2019). "It is becoming established that tumor cells express EpCAM at varying levels." (PMID 31174404, 2019). "For the first pair of samples, we obtained 1905 epithelial cells based on the expression of EpCAM, and from these identified tumor cells based on the microsatellite stability, and trained a model to detect differences between tumor and non-tumor epithelial cells." (PMID 31829268, 2019). "CECs and CTCs are cells that are shed into the bloodstream from the primary tumor and express epithelial cell surface (CD) markers as well as tumor-specific markers, in addition to frequently expressing epithelial markers that include the epithelial cell adhesion molecule (EpCAM) or cytokeratins." (PMID 31791269, 2019). "EpCAM is expessed by most adenocarcinomas and is thought to participatein tumor progression." (PMID 31709180, 2019). "Due to most of the studies identified EpCAM as a prognostic marker for cancer progression, it can be assumed that high expression for EpCAM in the tumor cells may be a useful criterion for specific identification of the CSCs within the tumor milieu." (PMID 31057717, 2019). "Therefore, CD3xEpCAM antibody binds to both mouse CD3ɛ and human EpCAM and redirects OT1 T cells to kill B16/EpCAM tumor cells in a target-specific manner by essentially changing the CD8 T cell specificity from OVA to EpCAM." (PMID 31825302, 2019). "The main disadvantage of the CellSearch® system is that it uses an EpCAM-based enrichment, a marker that might be downregulated in certain disseminated tumor cells." (PMID 30943928, 2019).
tumor (continued). "Moreover, flow cytometry of the disaggregated tumors indicated that a subset was GFP-positive (native fluorescence), and a subset was GFP+/EpCAM+, but the GFPhigh/EpCAMhigh population was only detected in tumor samples." (PMID 30546048, 2018). "EpCAM overexpression was confirmed by IHC in xenograft tumours derived from S18-EpCAM cells." (PMID 29305578, 2018). "Interestingly, circulating cells with this dual phenotype are EpCAM- and are therefore distinct form the more commonly studied EpCAM+ circulating tumor cells." (PMID 29868579, 2018). "Therefore, in this study we assessed HCC heterogeneity according to the presence of HPC markers DLK1, NCAM, EpCAM, and CK19 in the tumour, and analysed their association with HCC prognosis." (PMID 29774107, 2018). "A potential therapeutic utility might be considered when a patient’s primary tumor is positive for EpCAM expression." (PMID 30116994, 2018). "Furthermore, tumor‐suppressive miRNAs, including miR‐451a,39 miR‐15a,40 and miR‐363,41 were hypermethylated and down‐regulated in EpCAM+/CD44+ GC cells." (PMID 29862663, 2018). "Stratification of patients within the TCGA cohort according to tumor size disclosed higher expression of EpCAM expression in bigger tumors (T-classification 3–4 versus 1–2) (Mann-Whitney p-value = 0.013), whereas Sox2 and vimentin expression did not correlate with tumor size." (PMID 30275505, 2018). "Collectively, the seven different cellular subgroups might reflect the heterogeneity of the composition of EpCAM+ tumor cells and CD45+ tumor-infiltrating immune cells." (PMID 30389926, 2018). "Moreover, upregulated Prx II correlates with the expression of HCC-related stemness markers such as epithelial cell adhesion molecule (EpCAM) and keratin 19 and induces tumor initiation abilities." (PMID 30177619, 2018). "EpCAM-/CD44+ cells may represent tumor cells that have undergone EMT and/or are circulating cancer stem cells (cCSCs)." (PMID 29868579, 2018). "For example in the EpCAM-positive group which was shown to have poor prognosis, many tumours also expressed other HPC markers in different combinations, indicating that EpCAM-positive HCCs are highly heterogeneous regarding the presence of the other HPC markers." (PMID 29774107, 2018). "Several effector cells, i.e., PBMC, NK, CAR-T were tested and validated as well as biological molecules such as Bi-specific T cell Engagers (BiTEs) targeting the EpCAM protein expressed on tumor cells and blocking antibodies against the immune checkpoint inhibitor PD-1." (PMID 29499048, 2018). "Increased γH2AX expression was found in tumour xenografts of PC-3-EpCAM-KD CaP cells compared to PC-3-EpCAM-scr group after RT, suggesting that sensitisation of CaP to RT could be mediated by KD of EpCAM in vivo." (PMID 30419852, 2018). "EpCAM could serve as a biomarker for tumor-initiating cells in HCC, because EpCAM-positive CTCs are considered a subtype of circulating cancer stem cells with stronger metastatic potential." (PMID 30126375, 2018). "The CellSearch CTC assay, the only currently United States Food and Drug Administration approved system, enriches CTCs based on the detection and identification of the epithelial cell adhesion molecule (EpCAM) and pan-cytokeratins in the tumor cell membrane and cytoplasm." (PMID 29467948, 2018). "Tumor-initiating cells enriched for CD133/CXCR4/EpCAM are highly metastatic." (PMID 30486409, 2018). "The intratumoral heterogeneity as well as a potential transition toward a more mesenchymal phenotype could partly explain why EpCAM-based methods only detect a fraction of the CTCs, despite the epithelial origin of the tumor." (PMID 30115931, 2018). "In addition, treatment with EpCAM-specific CAR-NK-92 cells significantly suppressed tumor growth compared with the Ctrl-NK-92 cells." (PMID 30410941, 2018).